UBE2K (ubiquitin conjugating enzyme E2 K)
Description:
Accepts ubiquitin from the E1 complex and catalyzes its covalent attachment to other proteins. In vitro, in the presence or in the absence of BRCA1-BARD1 E3 ubiquitin-protein ligase complex, catalyzes the synthesis of 'Lys-48'-linked polyubiquitin chains. Does not transfer ubiquitin directly to but elongates monoubiquitinated substrate protein. Mediates the selective degradation of short-lived and abnormal proteins, such as the endoplasmic reticulum-associated degradation (ERAD) of misfolded lumenal proteins. Ubiquitinates huntingtin. Proposed to be involved in ubiquitination and proteolytic processing of NF-kappa-B; in vitro supports ubiquitination of NFKB1. In case of infection by cytomegaloviruses may be involved in the US11-dependent degradation of MHC class I heavy chains following their export from the ER to the cytosol. In case of viral infections may be involved in the HPV E7 protein-dependent degradation of RB1.
Synonyms: HIP2; LIG; HYPG; UBC1; E2-25K
Tractability: Small molecule: a structure with a bound ligand is known; it has a high-quality binding pocket. Antibody: the Human Protein Atlas places it where antibodies can reach. PROTAC: UniProt records ubiquitination sites on it; ubiquitination databases record sites on it; its protein half-life has been measured.
Target class: Enzyme; Transferase
Gene: Protein-coding gene on chromosome 4 (39,698,109 to 39,782,792, forward strand). Ensembl gene ENSG00000078140.
Subcellular location: Cytoplasm
Subcellular location (Human Protein Atlas): Cytosol; Plasma membrane
Pathways (Reactome):
Immune System: Antigen processing: Ubiquitination & Proteasome degradation; Negative regulators of DDX58/IFIH1 signaling
Metabolism of proteins: Synthesis of active ubiquitin: roles of E1 and E2 enzymes
Gene Ontology:
Molecular function: protein binding; ubiquitin protein ligase binding; ubiquitin-protein transferase activity; ubiquitin-ubiquitin ligase activity; ubiquitin conjugating enzyme activity
Biological process: cellular response to interferon-beta; free ubiquitin chain polymerization; positive regulation of peptidyl-threonine phosphorylation; positive regulation of tumor necrosis factor-mediated signaling pathway; positive regulation of type I interferon-mediated signaling pathway; protein K48-linked ubiquitination; protein polyubiquitination; ubiquitin-dependent protein catabolic process; protein ubiquitination
Cellular component: cytoplasm; cytosol; filopodium tip; nucleus
Genetic constraint (gnomAD): Loss-of-function variants: 3 observed, 10.65 expected, observed/expected ratio (o/e) 0.28, 90% interval 0.13 to 0.73. The upper end of that interval is the gene's LOEUF score, 0.73, which puts it in group 2 of 6, group 1 being the genes least tolerant of losing a copy. Missense variants: 32 observed, 106.27 expected, observed/expected ratio (o/e) 0.3, 90% interval 0.23 to 0.4. Synonymous variants: 44 observed, 39.95 expected, observed/expected ratio (o/e) 1.1, 90% interval 0.86 to 1.42.
Homologues: Orthologues: chimpanzee UBE2K (100% identical), guinea pig UBE2K (100% identical), mouse Ube2k (100% identical), rabbit UBE2K (100% identical), dog UBE2K (99% identical), tropical clawed frog ube2k (98% identical), zebrafish ube2kb (97% identical), macaque UBE2K (90% identical), rat Ube2k (90% identical), zebrafish ube2ka (86% identical), pig UBE2K (78% identical), Drosophila melanogaster Ubc4 (68% identical). Paralogues in human: UBE2N (36% identical), UBE2NL (33% identical), UBE2R2 (28% identical), UBE2T (28% identical), CDC34 (28% identical), UBE2O (26% identical), UBE2J1 (25% identical), UBE2C (24% identical), UBE2G1 (24% identical), UBE2A (23% identical), UBE2B (23% identical), UBE2F (23% identical), and 12 more.
Diseases named in the same sentence as UBE2K in open-access papers:
UBE2K is named in the same sentence as 40 diseases in open-access papers, as found by Europe PMC text mining. Sharing a sentence is not in itself a finding about the gene and the disease. The quoted sentences say what the papers report.
schizophrenia (5 papers, 2020 to 2024). A major psychotic disorder characterized by abnormalities in the perception or expression of reality. "Ube2k enzyme and mRNA transcription levels are increased in blood and brain tissue from post-mortem schizophrenia patients." (PMID 32403399, 2020). "UBE2K was reported to be correlated with positive symptoms of psychosis in schizophrenia and bipolar patients." (PMID 32223758, 2020). "Another ubiquitin conjugating enzyme (Ubiquitin Conjugating Enzyme E2 K; UBE2K) was also associated with schizophrenia, and this association is hypothesized to be driven by elevated levels of ubiquitinated proteins." (PMID 36980961, 2023). "In addition, ubiquitin-conjugating enzyme (UBE2K) (a hub gene of schizophrenia Module 1 ubiquitin-mediated proteolysis pathway) has been found to be associated with positive symptom domains of psychosis." (PMID 37861850, 2022).
breast cancer (4 papers, 2014 to 2024). A primary or metastatic malignant neoplasm involving the breast. "Few targeted genes of fs-cb-miRs like TNS1 (Cte-miR824-3p), UBE2K (Cte-miR168), FNDC3A (Cte-miR6183) and PAPD4 (Cte-miR7780-3p) were involved in malignant tumors of the breast, Alzheimer’s disease, Angelman syndrome and Hepatitis C virus infection, respectively." (PMID 38674383, 2024).
gastric cancer (4 papers, 2014 to 2022). A primary or metastatic malignant neoplasm involving the stomach. "Both UbcH10 and Ube2S are overexpressed in human cancers and elevated expression of Ube2K is associated with a poor prognosis in pancreatic and gastric cancers." (PMID 34586382, 2021).
hepatocellular carcinoma (3 papers, 2023 to 2025). A malignant tumor that arises from hepatocytes. "UBE2K could promote the progression of hepatocellular carcinoma via the regulation of c-Myc." (PMID 36911406, 2023).
pancreatic cancer (2 papers, 2023 to 2025). "The findings suggest that LINC00578 mediates the inhibition of ferroptosis in pancreatic cancer by specifically interacting with UBE2K, thereby impeding the ubiquitination process of SLC7A11, and consequently fostering the progression of pancreatic cancer." (PMID 39827195, 2025). "Taken together, this study revealed that LINC00578 promoted pancreatic cancer progression and inhibited ferroptosis by directly binding UBE2K to suppress SLC7A11 ubiquitination." (PMID 36846713, 2023). "This study illustrates that LINC00578 promotes pancreatic cancer cell progression and suppresses ferroptosis by directly binding UBE2K to inhibit the ubiquitination of SLC7A11." (PMID 36846713, 2023). "Furthermore, we mechanistically explored whether LINC00578 inhibits ferroptosis in pancreatic cancer cells by reducing ubiquitin-conjugating enzyme 2K- (UBE2K-) mediated SLC7A11 degradation." (PMID 36846713, 2023). "This study elucidated that LINC00578 acts as an oncogene to promote pancreatic cancer cell progression and suppress ferroptosis by directly combining with UBE2K to inhibit the ubiquitination of SLC7A11, which provides a promising option for the diagnosis and treatment of pancreatic cancer." (PMID 36846713, 2023).
Parkinson disease (2 papers, 2024). A progressive degenerative disorder of the central nervous system characterized by loss of dopamine producing neurons in the substantia nigra and the presence of Lewy bodies in the substantia nigra and locus coeruleus. "Another example in Parkinson’s disease is the E2 UBE2K, whose expression is decreased in the substantia nigra of patients." (PMID 39596581, 2024).
amyotrophic lateral sclerosis (1 paper, 2024). Amyotrophic lateral sclerosis (ALS) is a neurodegenerative disease characterized by progressive muscular paralysis reflecting degeneration of motor neurons in the primary motor cortex, corticospinal tracts, brainstem and spinal cord. "This same E2 Ube2k is up-regulated in the spinal cord of SOD1-G93A mice, a model of amyotrophic lateral sclerosis (ALS), another NDs." (PMID 39596581, 2024).
depression (1 paper, 2024). "Functionally, circ-UBE2K-overexpressing mice exhibited worsened depression-like symptoms, elevated brain inflammatory factor levels, and abnormal microglial activation." (PMID 38994030, 2024). "Mechanistically, we found that circ-UBE2K interacts with the HNRNPU protein to regulate UBE2K protein expression, mediate abnormal microglial activation, and promote the progression of depression." (PMID 38994030, 2024). "Then, we confirmed the function of circ-UBE2K and the specific mechanism by which it binds to the HNRNPU protein to regulate UBE2K protein expression and mediate abnormal microglial activation to promote the development of depression." (PMID 38994030, 2024). "After database screening, qPCR validation, and clinical correlation analysis, it was found that circ-UBE2K was highly expressed in blood samples from patients with depression." (PMID 38994030, 2024). "By studying changes in the peripheral blood of MDD patients and depression model animals together with changes in the expression of circ-UBE2K in vivo and in vitro." (PMID 38994030, 2024). "This study provides new evidence that circ-UBE2K alleviates depressive-like behavior through the regulation of microglial function and suggests that circ-UBE2K may serve as a potential therapeutic target for the treatment of severe depression." (PMID 38994030, 2024). "Our findings link the epigenetic regulation of depression with abnormal activation of microglia and circ-UBE2K, providing evidence that circUBE2K may be a new therapeutic target for MDD." (PMID 38994030, 2024). "To further confirm the role of circ-UBE2K in depression model mice, we specifically knocked down circ-UBE2K in microglia to determine whether inhibition of circ-UBE2K can attenuate depression-like behavior in mice." (PMID 38994030, 2024). "Therefore, we constructed a chronic unpredictable mild stress (CUMS)-induced depression mouse model and measured the levels of circ-UBE2K in the brain tissue and peripheral blood of depression model mice and normal control mice." (PMID 38994030, 2024). "We further evaluated whether circ-UBE2K in these cells was upregulated in the brains of depression model mice." (PMID 38994030, 2024). "Downregulation of circ-UBE2K may thus represent a potential therapeutic target for depression." (PMID 38994030, 2024). "Consistent with previous human studies, circ-UBE2K was highly expressed in the brain tissue and peripheral blood of CUMS-induced depression model mice." (PMID 38994030, 2024). "Then, we examined the correlation between the circ-UBE2K and circ-TTC8 expression level in peripheral blood and scores on the Hamilton Depression Scale (HAMD-17 and HAMD-24) in patients with depression." (PMID 38994030, 2024).
memory impairment (1 paper, 2023). "We revealed an essential role of the upregulated circRIMS2/miR-3968 pathway in mediating synaptic and memory impairments in AD through activating the UBE2K-mediated ubiquitination and degradation of GluN2B." (PMID 38012808, 2023).
myeloma (1 paper, 2022). "The use of the drug ixazomib reportedly inhibited myeloma cell growth by significantly increasing HIST1H2BD expression and reducing UBE2K expression." (PMID 36466549, 2022).
narcolepsy (1 paper, 2025). A sleep disorder characterized by a tendency for excessive sleepiness during the day which occurs even after adequate sleep in the nighttime. "UBE2K was identified as a target of the central nervous system stimulant, dextroamphetamine, used to treat attention-deficit disorder (ADHD) and narcolepsy, however its use has been federally controlled due to the high potential for abuse." (PMID 40034430, 2025).
osteoporosis (1 paper, 2019). A condition of reduced bone mass, with decreased cortical thickness and a decrease in the number and size of the trabeculae of cancellous bone (but normal chemical composition), resulting in increased fracture incidence. "We identified three hub genes that might associate with osteoporosis including BRCC3, UBE2N, and UBE2K." (PMID 30834083, 2019). "Then, three hub genes that have strong protein and protein interactions and might be associated with osteoporosis were identified, including BRCC3, UBE2N, and UBE2K." (PMID 30834083, 2019). "The mRNA expressions of UBE2N and UBE2K not changed in osteoblasts from osteoporosis patients compared with healthy donors, while the mRNA expression of BRCC3 was significantly increased." (PMID 30834083, 2019). "UBE2N mRNA and UBE2K mRNA were not changed in osteoblasts isolated from osteoporosis patients, compared with healthy donors, whereas BRCC3 mRNA was significantly increased." (PMID 30834083, 2019).
tumor (8 papers, 2015 to 2025). "An analysis of the relationships between GRSF1 and tumor stem cell markers revealed significant positive associations with UBE2K, XRCC5, SNRPD3, and CDC123 (Appendix B Figure A2c), which was consistent with previous findings." (PMID 40722682, 2025).
cancer (7 papers, 2014 to 2025). A tumor composed of atypical neoplastic, often pleomorphic cells that invade other tissues. "The limited sample size in our study must be carefully considered, and therefore, any conclusions regarding UBE2K in BRAF-mutated cancer cannot be made." (PMID 40080754, 2025). "Although the expression of UBE2K is known to have a prognostic value in HCC, any potential role of UBE2K in BRAF-mutated cancer has not been established." (PMID 40080754, 2025). "One possibility is that Ube2S may function as the predominant chain-extending enzyme in normal cells, but that Ube2K can acquire that role when it is overexpressed in cancer cells." (PMID 34586382, 2021).
neurodegenerative disease (4 papers, 2018 to 2023). A disorder of the central nervous system characterized by gradual and progressive loss of neural tissue and neurologic function. "The E2 Ub conjugating enzyme UBE2K, also known as huntingtin-interacting protein 2 (HIP2), is also a potential modifier of neurodegenerative diseases." (PMID 34689261, 2022).
neurological diseases (3 papers, 2020 to 2025). "These loci implicate genes highly expressed in brain and previously connected to neurological diseases (UBE2K, FRMD4B, the HLA gene complex)." (PMID 32699239, 2020).
UBE2K also shares sentences with these, for which no sentence is quoted: bladder cancer (14 papers); Alzheimer disease (2); infection (2); psychosis (2); acute myeloid leukemia (1); Angelman syndrome (1); Cerebral ischemia (1); cervical cancer (1); colon cancer (1); colorectal cancer (1); esophageal squamous cell carcinoma (1); glioblastoma multiforme (1); hepatitis C virus infection (1); Huntington disease (1); kidney (1); liver cancer (1); lung carcinoma (1); malaria (1); pancreatitis (1); prostate carcinoma (1); Rett syndrome (1); Stroke (1); virus infection (1); visceral leishmaniasis (1).